INHBB (inhibin subunit beta B)
Diseases named in the same sentence as INHBB in open-access papers (continued):
Sharing a sentence is not in itself a finding about the gene and the disease.
cancer (17 papers, 2009 to 2025). A tumor composed of atypical neoplastic, often pleomorphic cells that invade other tissues. "We further performed leading edge analysis and found a close association between INHBB and these cancer-promoting pathways." (PMID 33083477, 2020). "INHBB is a potential prognostic biomarker for GC and may drive the abnormal activity of critical cancer-associated pathways, potentially contributing to immune cell infiltration to promote GC development." (PMID 36118865, 2022). "In this pilot study, we identified that INHBB expression is positively correlated with the infiltration of macrophages, endothelial cells, and cancer-associated fibroblasts and is negatively associated with the infiltration of CD4+/CD8+ T cells and plasmacytoid dendritic cells." (PMID 36118865, 2022). "Therefore, we explored the association between the expression of INHBB and immunoinhibitors/immunostimulators in several cancer types." (PMID 36118865, 2022). "Interestingly, this gene was previously identified as a regulator of hormone secretion from the pituitary gland but, more recently, INHBB expression has been associated with cancer, although its role in EMT remains controversial." (PMID 33291363, 2020). "INHBB, a member of the TGF-β superfamily, is positively associated with the infiltration of macrophages, endothelial cells, and cancer-associated fibroblasts." (PMID 40705171, 2025). "INHBB is involved in various biological processes, including cell proliferation and apoptosis, making it an important candidate in cancer research." (PMID 39850875, 2024). "For example, for liver cancer, it was found that Sox9/INHBB axis mediated crosstalk between cancer cells and hepatic stellate cells and promoted the metastasis of hepatocellular carcinoma." (PMID 37858201, 2023). "The Western blot and qRT-PCR data of GC tissues from our hospital showed that the INHBB level in GC tissues was higher than that in non-cancer tissues." (PMID 37858201, 2023). "The results of Kaplan-Meier analysis indicated that high INHBB expression was related to a poor prognosis of overall survival (OS) in seven cancer types, which is contrary to that in THCA, including BLCA, COAD, GBMLGG, HNSC, COADREAD MESO and UVM." (PMID 36118865, 2022). "The results of the heatmap demonstrated a significant correlation between several chemokines/chemokine receptors and INHBB expression in pan-cancers." (PMID 36118865, 2022). "GSEA showed that INHBB was closely correlated with 5 cancer-promoting signaling pathways including the Hedgehog signaling pathway, ECM receptor interaction, TGF-β signaling pathway, focal adhesion, and pathway in cancer." (PMID 33083477, 2020). "Pathways in cancer contain the regulation of many cancer-promoting pathways including these 4 signaling pathways, which suggests that INHBB regulates CRC by mediating these cancer-promoting pathways." (PMID 33083477, 2020). "Some studies suggest that increased INHBB expression may promote epithelial-mesenchymal transition (EMT) in cancer cells, thereby enhancing their metastatic potential." (PMID 39850875, 2024). "Previous studies have shown that INHBB exhibits a complex dual role in different types of cancer." (PMID 39850875, 2024). "Recently, INHBB was regarded as a valuable biomarker in various cancer types." (PMID 36118865, 2022). "Inhibin subunit beta B (INHBB) is a potential prognostic biomarker for a variety of cancers." (PMID 36118865, 2022). "In addition, we downland two GEO datasets (GSE26899, and GSE29272) to validate the transcription expression level of INHBB in cancer tissues and adjacent tissues." (PMID 36118865, 2022). "Recently, INHBB has been considered a novel oncogene in various cancer types." (PMID 33083477, 2020). "Novel DNA methylation biomarkers for the prognosis during the early stages of cancer, such as INHBB, SMOC2, BDNF, and TBRG4, are being tested for clinical use to improve detection methods and guide the treatment and diagnoses of cancer patients." (PMID 34827720, 2021).
cancer (continued). "Our findings provide significant new information on the specific cancers impacted by the genes investigated here, INHA, INHBA, INHBB, ENG and TGFFBR3, and shed light on potential functional dependencies." (PMID 33819300, 2021). "In many cancers, including CRC, as well as oral, endometrial, prostate, renal, and thyroid cancer, INHBB is overexpressed." (PMID 34827720, 2021). "This suggested that, as individual genes, INHBB, LAMA1, SCGB3A1 and OPG can indeed promote metastatic colonization, and that coexpression of the four genes may provide a further advantage to cancer cells." (PMID 35469015, 2022). "INHBB on the other hand had no predictive value in the assessed cancer types." (PMID 33819300, 2021).
INHBB also shares sentences with these, for which no sentence is quoted: hepatocellular carcinoma (2 papers); oral cancer (2); Bardet-Biedl syndrome (1); benign pheochromocytomas (1); benign prostatic hyperplasia (1); brain cancer (1); COVID-19 (1); digestive system cancer (1); female infertility (1); fibrosis (1); Glucose intolerance (1); head and neck cancer (1); Hypertension (1); hyperuricemia (1); hypogonadism (1); infection (1); kidney cancer (1); Kidney Disease (1); leukemia (1); Lymphatic Metastasis (1); metabolic disease (1); metastatic tumor (1); myeloma (1); Noonan syndrome (1); osteoarthritis (1); ovarian cancer (1); ovarian failure (1); pancreatic cancer (1); polycystic kidney disease (1); pulmonary arterial hypertension (1).
A further 6 diseases each share a sentence with INHBB in 1 paper.